SHANK1 (SH3 and multiple ankyrin repeat domains 1)
Description:
Seems to be an adapter protein in the postsynaptic density (PSD) of excitatory synapses that interconnects receptors of the postsynaptic membrane including NMDA-type and metabotropic glutamate receptors via complexes with GKAP/PSD-95 and Homer, respectively, and the actin-based cytoskeleton. Plays a role in the structural and functional organization of the dendritic spine and synaptic junction.
Synonyms: SSTRIP; SPANK-1; synamon
Tractability: Small molecule: a structure with a bound ligand is known. Antibody: its Gene Ontology location is reachable by antibodies, with high confidence; the Human Protein Atlas places it where antibodies can reach. PROTAC: ubiquitination databases record sites on it; its protein half-life has been measured.
Gene: Protein-coding gene on chromosome 19 (50,659,255 to 50,719,802, reverse strand). Ensembl gene ENSG00000161681.
Subcellular location: Cytoplasm; Postsynaptic density; Synapse
Subcellular location (Human Protein Atlas): Plasma membrane
Pathways (Reactome):
Neuronal System: Neurexins and neuroligins
Gene Ontology:
Molecular function: protein binding; ankyrin repeat binding; identical protein binding; ionotropic glutamate receptor binding; protein-containing complex binding; scaffold protein binding; SH3 domain binding; somatostatin receptor binding; synaptic receptor adaptor activity; G protein-coupled receptor binding; signaling receptor complex adaptor activity; structural constituent of postsynaptic density
Biological process: adult behavior; determination of affect; social behavior; vocalization behavior; AMPA selective glutamate receptor signaling pathway; associative learning; dendritic spine morphogenesis; long-term memory; negative regulation of actin filament bundle assembly; neuromuscular process controlling balance; positive regulation of dendritic spine development; positive regulation of excitatory postsynaptic potential; protein localization to synapse; protein-containing complex assembly; synapse maturation; synapse organization; cognition; habituation; maintenance of postsynaptic density structure; modulation of chemical synaptic transmission; olfactory behavior; righting reflex
Cellular component: membrane; plasma membrane; cytosol; dendrite; dendritic spine; excitatory synapse; neuron projection; postsynaptic density; postsynaptic membrane; cytoplasm; glutamatergic synapse; Schaffer collateral - CA1 synapse; synapse
Genetic constraint (gnomAD): Loss-of-function variants: 35 observed, 121.08 expected, observed/expected ratio (o/e) 0.29, 90% interval 0.22 to 0.38. The synonymous counts are far from expectation, so gnomAD's model fits this gene poorly and the ratio says little. Missense variants: 2,584 observed, 2,448.4 expected, observed/expected ratio (o/e) 1.06, 90% interval 1.02 to 1.09. Synonymous variants: 1,377 observed, 1,087.9 expected, observed/expected ratio (o/e) 1.27, 90% interval 1.21 to 1.32.
Gene-disease validity (ClinGen):
ClinGen rates the evidence that SHANK1 causes each of these diseases.
complex neurodevelopmental disorder (autosomal dominant): Definitive. A disorder that involves more than one phenotype associated with the central nervous system, including but not limited to intellectual disability, autism, and seizures (epilepsy).
Homologues: Orthologues: macaque SHANK1 (99% identical), chimpanzee SHANK1 (99% identical), dog SHANK1 (96% identical), mouse Shank1 (94% identical), rat Shank1 (94% identical), pig SHANK1 (92% identical), guinea pig SHANK1 (76% identical), tropical clawed frog shank1 (40% identical), zebrafish shank1 (25% identical), Drosophila melanogaster Prosap (16% identical), Caenorhabditis elegans shn-1 (14% identical). Paralogues in human: SHANK2 (37% identical), SHANK3 (33% identical).
Diseases named in the same sentence as SHANK1 in open-access papers:
SHANK1 is named in the same sentence as 42 diseases in open-access papers, as found by Europe PMC text mining. Sharing a sentence is not in itself a finding about the gene and the disease. The quoted sentences say what the papers report.
autism (30 papers, 2011 to 2025). Persistent deficits in social interaction and communication and interaction as well as a markedly restricted repertoire of activity and interest as well as repetitive patterns of behavior. "SHANK1 is a synapse-associated protein generally expressed in the nervous system and is closely related to disorders such as autism." (PMID 39765560, 2024). "Here, we propose a novel de novo mosaic p.(Gly126Arg) SHANK1 variant as the monogenic cause of disease in a patient who presented, from the age of 2 years, moderate intellectual disability, autism, and refractory epilepsy of the Lennox-Gastaut type." (PMID 34912368, 2021). "In line A_333N, two mutations had very strong association scores as potential modifiers: A mutation in SH3 and multiple ankyrin repeat domains 1 (Shank1) was a strong candidate gene based on its autism associations, whereas a mutation in Fan1 would be consistent with the DDR pathway." (PMID 32317254, 2020). "A rare inherited deletion encompassing the Shank1 gene has been associated with autism in males, whereas only anxiety and shyness behaviors were observed in females, suggesting that Shank1 deletion could have sex-dependent effects." (PMID 28331639, 2017). "Mutations in SHANK1 are only present in males with a normal IQ and autism." (PMID 26052415, 2015). "Lower penetrance in females has been shown for a rare CNV (microdeletion) in the autosomal autism risk gene SHANK1 in a 4-generation family, where in males it is associated with high-functioning ASD with or without increased anxiety, but in females it is associated only with increased anxiety." (PMID 25524786, 2015). "To test the hypothesis that a mutation in SHANK1 contributes to the symptoms of autism, we evaluated Shank1−/− null mutant, Shank1+/− heterozygote, and Shank1+/+ wildtype littermate control mice for behavioral phenotypes with relevance to autism." (PMID 21695253, 2011). "To test the hypothesis that a mutation in SHANK1 contributes to the symptoms of autism, we evaluated Shank1−/− null mutant mice for behavioral phenotypes with relevance to autism, focusing on social communication." (PMID 21695253, 2011). "In a Shank1 knockout mouse model used to study the autism spectrum, mild anxiety-like behaviors were identified in 6- to 7-week-old individuals, which is consistent with our findings." (PMID 40143332, 2025). "Numerous RG/RGG-containing proteins have been implicated in neurological disorders, such as FUS and TAF-15 in ALS, FXR1, and FMRP1 in fragile X syndrome (FSX), SMN in spinal muscular atrophy (SMA), SHANK1 in autism, as well as a plethora of human cancers." (PMID 35203243, 2022). "The reduced levels of ultrasonic vocalizations and scent marking behavior in Shank1−/− mice are consistent with a phenotype relevant to social communication deficits in autism." (PMID 21695253, 2011). "SHANK1 and CLASP1 were co-identified in three types of DEPs, which may perform a key function in the pathogenic mechanism of autism and the therapeutic effect of DBS." (PMID 36474209, 2022). "Mutations in SHANK1–3 are prevalent in patients with autism spectrum disorders (ASD), and loss of one copy of SHANK3 causes Phelan-McDermid Syndrome, a syndrome in which Autism occurs in >80% of cases." (PMID 30405356, 2018). "Although no cases of mutations in SHANK1 have yet been identified in individuals with autism, SHANK1 is a member of the SHANK gene family, in which mutations in SHANK2 and SHANK3 have been detected in several autistic individuals." (PMID 21695253, 2011). "While SHANK1 has not been associated with autism, mutations in SHANK2 and SHANK3, other members of the SHANK gene family, appear in several individuals with autism." (PMID 21695253, 2011).
autism (continued). "Interestingly, a study using a transgenic model of autism (Shank1 knock-out) reported an increase in Bdnf transcript levels in Shank1 knock-out animals only after an object recognition task and not at baseline, and levels were negatively correlated with object recognition memory." (PMID 34439657, 2021). "Interestingly, of the autism genes positively correlated with δ-catenin, there is a significant enrichment in genes involved in dendrite morphogenesis, including PDLIM5, SHANK1, CDKL5, and DLG4." (PMID 27822498, 2016).
Anxiety (13 papers, 2011 to 2025). Intense feelings of nervousness, tension, or panic often arise in response to interpersonal stresses. "Shank1 null mutant mice show decreased transitions in the light-dark test, suggesting anxiety-related phenotypes and reduced motor abilities." (PMID 33519379, 2020). "Shank1 knock-out mice show increased anxiety, decreased vocal communication, decreased locomotion and remarkably, enhanced working memory, but decreased long-term memory." (PMID 25188300, 2014). "Shank1 KO mice: Shank1 KO mice show significantly decreased locomotor capabilities, enhanced anxiety-like behavior, and decreased fear conditioning behavior and maintenance of spatial learning." (PMID 24287856, 2013). "Behaviorally, Shank1−/− mice displayed reduced locomotion, impaired rotarod performance, higher anxiety-like behavior, but normal levels of social interactions." (PMID 21695253, 2011). "The Shank1 mice model of ASD manifests mild anxiety and repetitive behavior." (PMID 33519379, 2020). "However, in the elevated plus maze test, the Sh‐SHANK1 rats exhibited a significant increase in the open arm entry ratio without affecting the duration in the open arm ratio, indicating heightened anxiety‐like behavior." (PMID 40574425, 2025). "Of note, the time spent in the center was not affected by AMPH or MDMA treatment in a genotype-dependent manner and the reduction in center time seen following Shank1 deletion might reflect a mild increase in anxiety levels and is consistent with the literature." (PMID 30505269, 2018). "Shank1 R882H-KI mice displayed core symptoms of ASD, namely, social disability and repetitive behaviors, without confounding comorbidities of abnormal motor function and heightened anxiety." (PMID 35388181, 2022). "Mice completely lacking all Shank1 protein isoforms (Shank1–/– mice) have increased anxiety-related behavior, impaired contextual fear memory and object recognition memory, as well as social communication/interaction deficits." (PMID 30627085, 2018). "Behavioral characterization of Shank1 P1812L-KI mice showed that HET mice manifested two core traits of ASD without comorbidities such as abnormal locomotion or anxiety-like behaviors, which are confounding factors for the interpretation of outcomes in assays for social behaviors and RRBs." (PMID 37880287, 2023). "However, it appears unlikely that the genotype difference in pup USV is due to a difference in anxiety levels, since one would have expected more, but not less USV in Shank1−/− mice that display higher levels of anxiety-related behavior." (PMID 21695253, 2011). "Interestingly, sex differences might modulate the phenotype since females carrying an inherited SHANK1 deletion exhibited anxiety and shyness, but did not fulfill criteria for ASD." (PMID 25188300, 2014).
autism spectrum disorder (9 papers, 2017 to 2025). A spectrum of developmental disorders that includes autism, and Asperger syndrome. "Molecular defects of SHANK3 are a well-known cause of several neurodevelopmental entities, in particular autism spectrum disorders and epilepsy, whereas relatively little is known about disease associations of SHANK1." (PMID 34912368, 2021). "Multiple point mutations, deletions, and truncations occur in SHANK1–3 in people with autism spectrum disorders (ASD), with SHANK3 mutations mainly found in ASD individuals with moderate to severe intellectual disability." (PMID 30405356, 2018). "Our results suggest that EZH2 is involved in regulating ZIC2 and SHANK1 which have been linked to neurological diseases such as autism spectrum disorder." (PMID 28720872, 2017). "The genes Shank1 and Shank2 (containing 74 and 394 pG4-BS regions, respectively) encode proteins that are members of the Shank family of proteins functioning as molecular scaffolds in excitatory synapses, and whose deletion was associated with increased susceptibility to autism spectrum disorder." (PMID 37094040, 2023). "An association between cases of autism spectrum disorder (ASD) and mutations in the genes SH3 and multiple ankyrin repeat domains protein 1 (SHANK1), SHANK2 and SHANK3 was reported in several large-scale genomic studies." (PMID 35468874, 2022). "Genetic defects in the three SH3 and multiple ankyrin repeat domains (SHANK) genes (SHANK1, SHANK2, and SHANK3) are associated with multiple major neuropsychiatric disorders, including autism spectrum disorder (ASD), schizophrenia (SCZ), and bipolar disorder (BPD)." (PMID 30505269, 2018).
Intellectual disability (7 papers, 2014 to 2021). "SHANK1 (0.04%) and SHANK2 (0.17%) mutations occurred less frequently and were present in individuals with ASD and normal IQ, and ASD with moderate intellectual disability." (PMID 28702161, 2017). "Specifically, SHANK1 mutations were found in individuals with ASD and normal intelligence, whereas SHANK2 and SHANK3 mutations were associated with mild and severe mental retardation, respectively." (PMID 26819149, 2016). "Although her son was born from uncontrolled pregnancy with high blood levels of phenylalanine and poorly adhered to low-phenylalanine diet himself, he also escaped the intellectual disability (IQ 80–85) indicating a possible joint modifying role of p.Pro1591Ala in SHANK1 and p.Pro1716Thr in SHANK3." (PMID 34900593, 2021). "Importantly, mutations in Shank family proteins (also known as ProSAP) such as Shank1, Shank2 and Shank3 have been implicated in ASD and intellectual disability." (PMID 28979184, 2017). "Besides determining the number of Pvalb neurons in PV+/- and PV-/- mice, we quantified the number of this interneuron subpopulation in two well-established ASD mouse models, i.e., Shank1-/- and Shank3B-/- mice, covering the extremes of the spectrum with a gradient in severity in mental retardation." (PMID 26819149, 2016).
epilepsy (6 papers, 2014 to 2025). A brain disorder characterized by episodes of abnormally increased neuronal discharge resulting in transient episodes of sensory or motor neurological dysfunction, or psychic dysfunction. "For example, SHANK3 variants are generally associated with more severe forms of epilepsy and cognitive impairment, while SHANK1 variants are linked to milder neurodevelopmental and epileptic presentations." (PMID 39596051, 2024). "SHANK1, SHANK2, and SHANK3 variants have been associated with the development of ASDs, but they are also increasingly recognized as contributing to epilepsy, particularly through their role in synaptic excitability and plasticity." (PMID 39596051, 2024).
schizophrenia (5 papers, 2012 to 2025). A major psychotic disorder characterized by abnormalities in the perception or expression of reality. "Intriguingly, transgenic expression of HERV-W ENV also led to impaired expression of several other genes that are implicated as genetic risk factors of schizophrenia and ASD, including Cacna1g, Ank3, Shank1, and Shank3." (PMID 40102613, 2025). "In two probands of these 14 families, we detected rare TREs in three genic regions (CALCOCO2 and FXN in one family, and SHANK1 in the other family) that were also identified in our primary schizophrenia cohort." (PMID 35546631, 2022). "In addition to including members of the Set1-like H3K4 methyltransferase family (Kmt2a, Kmt2b, Kmt2c, and Kmt2d), these modules also encompassed rare variant genes associated with schizophrenia and ASD (Setd1a, Cacna1g, Ank3, Shank1, and Shank3)." (PMID 40102613, 2025).
Cognitive impairment (4 papers, 2016 to 2025). Abnormal cognition is characterized by deficits in thinking, reasoning, or remembering. "Our findings enhance the understanding of SHANK1 in synaptic function and provide new insights into how its dysregulation contributes to cognitive impairments associated with long‐term high‐salt diet." (PMID 40574425, 2025). "The degree of related mutations and cognitive impairment between SHANK1-3 also differs: patients with SHANK3 mutations suffer more cognitive impairment than those with SHANK1 or SHANK2 mutations." (PMID 36846568, 2023). "CREB dephosphorylation by a PKA inhibitor led to decreased SHANK1 levels, dendritic damage, and subsequent cognitive impairments." (PMID 40574425, 2025). "In summary, these findings strongly demonstrate that SHANK1 downregulation leads to synaptic damage and cognitive impairments, further implicating SHANK1 as a critical player in synaptic and cognitive function." (PMID 40574425, 2025). "Our study identifies a novel mechanistic link between long‐term HS diet and cognitive impairment, wherein PKA/CREB axis inactivation leads to SHANK1 reduction, synaptic damage, and cognitive deficits." (PMID 40574425, 2025). "The study identifies a novel mechanistic link between long‐term HS diet and cognitive impairment, wherein PKA/CREB axis inactivation leads to SHANK1 reduction, synaptic damage, and cognitive deficits." (PMID 40574425, 2025). "Notably, PKA activation restored CREB phosphorylation and SHANK1 expression, significantly reversing synaptic and cognitive impairments induced by long‐term HS diet." (PMID 40574425, 2025). "In this report, we demonstrate that SHANK1 reduction leads to HS‐related cognitive deficits." (PMID 40574425, 2025). "Additionally, downregulation of SHANK1 exacerbates synaptic dysfunction and cognitive deficits, while upregulation of the PKA/CREB pathway increases SHANK1 expression, thereby improving synaptic damage and mitigating cognitive deficits." (PMID 40574425, 2025). "This study reveals that HS diet reduces SHANK1, a key postsynaptic scaffolding protein, via downregulation of the PKA/CREB pathway, leading to synaptic dysfunction and cognitive deficits in rats." (PMID 40574425, 2025).
fragile X syndrome (4 papers, 2018 to 2023). A genetic syndrome caused by mutations in the FMR1 gene which is responsible for the expression of the fragile X mental retardation 1 protein. "Unlike the preceding clusters which had topical focuses, Clusters #2 (manually renamed “Fragile X Syndrome”) and #3 (manually renamed “SHANK1,2,3 Genes”) are discussed together primarily because of the use of animal models in their research methodology (e.g., Refs." (PMID 36140813, 2022). "Therefore, proposed labels may be “Fragile X Syndrome” and “SHANK1,2,3 Genes” for Clusters #2 and #3, respectively." (PMID 36140813, 2022). "Accordingly, studies on Fragile-X syndrome (FXS) and Shank1 ASD-mouse models have shown a correlation between spine morphology, neuron functionality, and behavior, supporting the importance of proper dendritic spine morphology and density for normal synaptic plasticity and behavior." (PMID 30123108, 2018).
Asperger syndrome (2 papers, 2014 to 2022). "This type of improvement is also observed in some patients with ASD that are high-functioning or have Asperger’s syndrome or mice mutants for the ADS-related gene (NL3 KI/Shank1 KO), and it will be interesting to conduct a further study on this point." (PMID 35626639, 2022). "Accordingly, male individuals carrying SHANK1 deletions do not present with language delay or ID and are diagnosed with normal IQ ASD or Asperger syndrome." (PMID 25188300, 2014).